ARL2 (ARF like GTPase 2)
Description:
Small GTP-binding protein which cycles between an inactive GDP-bound and an active GTP-bound form, and the rate of cycling is regulated by guanine nucleotide exchange factors (GEF) and GTPase-activating proteins (GAP). GTP-binding protein that does not act as an allosteric activator of the cholera toxin catalytic subunit. Regulates formation of new microtubules and centrosome integrity. Prevents the TBCD-induced microtubule destruction. Participates in association with TBCD, in the disassembly of the apical junction complexes. Antagonizes the effect of TBCD on epithelial cell detachment and tight and adherens junctions disassembly. Together with ARL2, plays a role in the nuclear translocation, retention and transcriptional activity of STAT3. Component of a regulated secretory pathway involved in Ca(2+)-dependent release of acetylcholine. Required for normal progress through the cell cycle. Also regulates mitochondrial integrity and function.
Synonyms: ARFL2; MRCS1
Tractability: Small molecule: a structure with a bound ligand is known. PROTAC: UniProt records ubiquitination sites on it; ubiquitination databases record sites on it; its protein half-life has been measured.
Gene: Protein-coding gene on chromosome 11 (65,014,144 to 65,024,328, forward strand). Ensembl gene ENSG00000213465.
Subcellular location: Mitochondrion intermembrane space; Cytoplasm, cytoskeleton, microtubule organizing center, centrosome; Nucleus; Cytoplasm
Subcellular location (Human Protein Atlas): Basal body; Flagellar centriole; Nucleoplasm; Equatorial segment; Mid piece; Mitochondria; Nucleoli
Pathways (Reactome):
Metabolism of proteins: Post-chaperonin tubulin folding pathway
Signal Transduction: RAS processing
Transport of small molecules: Transport of nucleosides and free purine and pyrimidine bases across the plasma membrane
Gene Ontology:
Molecular function: GTP binding; GTPase activity; protein binding; GDP binding
Biological process: centrosome cycle; maintenance of protein location in nucleus; negative regulation of GTPase activity; positive regulation of microtubule polymerization; regulation of aerobic respiration; regulation of glycolytic process; regulation of microtubule polymerization; bicellular tight junction assembly; positive regulation of cell-substrate adhesion; protein folding
Cellular component: centrosome; cilium; mitochondrial intermembrane space; mitochondrion; nucleolus; nucleoplasm; nucleus; cytoplasm; cytosol; lateral plasma membrane; microtubule cytoskeleton; mitochondrial matrix
Genetic constraint (gnomAD): Loss-of-function variants: 10 observed, 18.15 expected, observed/expected ratio (o/e) 0.55, 90% interval 0.34 to 0.94. The upper end of that interval is the gene's LOEUF score, 0.94, which puts it in group 3 of 6, group 1 being the genes least tolerant of losing a copy. Missense variants: 215 observed, 236.81 expected, observed/expected ratio (o/e) 0.91, 90% interval 0.81 to 1.02. Synonymous variants: 111 observed, 98 expected, observed/expected ratio (o/e) 1.13, 90% interval 0.97 to 1.33.
Homologues: Orthologues: chimpanzee ARL2 (99% identical), dog ARL2 (99% identical), macaque ARL2 (99% identical), pig ARL2 (98% identical), mouse Arl2 (95% identical), guinea pig ARL2 (94% identical), rat Arl2 (86% identical), tropical clawed frog arl2 (86% identical), zebrafish arl2 (84% identical), Drosophila melanogaster Arl2 (74% identical), Caenorhabditis elegans evl-20 (62% identical). Paralogues in human: ARL3 (52% identical), ARF3 (46% identical), ARF1 (46% identical), ARF5 (45% identical), ARF4 (45% identical), TRIM23 (43% identical), ARF6 (42% identical), ARL5A (41% identical), ARL1 (40% identical), ARL5B (40% identical), ARL4C (38% identical), ARL14 (37% identical), and 18 more.
Diseases named in the same sentence as ARL2 in open-access papers:
ARL2 is named in the same sentence as 41 diseases in open-access papers, as found by Europe PMC text mining. Sharing a sentence is not in itself a finding about the gene and the disease. The quoted sentences say what the papers report.
breast carcinoma (7 papers, 2009 to 2025). "Decreased ARL2 expression was associated with resistance to cytotoxic agents in breast cancer cell lines." (PMID 33270982, 2021). "As a key regulator of microtubule, ARL2 has been implicated in several malignant tumors, such as breast cancer, cervical cancer, and pancreatic cancer." (PMID 29843637, 2018). "We have thus shown for the first time, in two different breast cancer cell models, that a reduced Arl2 expression level is associated with a more aggressive neoplastic phenotype." (PMID 19829707, 2009). "ARL2 has been shown to directly influence α/β-tubulin polymerization in the breast cancer cell line MCF-7." (PMID 32426352, 2020). "It has been reported that ARL2 expression level modifies cell morphology and influences mitotic and cytokinetic progression in breast cancer." (PMID 29843637, 2018). "ARL2 is considered to be involved in the regulation of tubulin peptide folding and microtubule dynamics in breast cancer cells." (PMID 25621032, 2015). "Given the reported tumor suppressor properties of PP2A, we have determined the impact of Arl2 on tumor cell aggressivity and tumorigenic capacity in two breast cancer cell models, MCF7 and MDA-MB-231." (PMID 19829707, 2009). "In this study, we show that Arl2 content is a major determinant of aggressive phenotype and tumorigenicity in two different breast cancer cell models, and low Arl2 expression levels appear to be correlated with enhanced aggressivity in the clinic." (PMID 19829707, 2009). "ARL2 was first reported to behave as a tumor suppressor in breast cancer." (PMID 32426352, 2020). "Moreover, in vitro assays using breast cancer cells depleted for ARL2 show less contact inhibition, an enhanced clonogenic potential and increased proliferation than control cells." (PMID 32426352, 2020). "In oncology, its identification of spatially resolved therapeutic targets—such as VEGFA and CD74 in glioblastoma, or ARL2 and TMEM145 in breast cancer—highlights its potential to uncover microenvironment-specific drivers of disease progression." (PMID 41275376, 2025). "Breast cancer cells expressing low level of ARL2 were not sensitive to contact inhibition, had a stronger clonogenic potential and an enhanced tumour growth." (PMID 33270982, 2021). "In conclusion these data suggest that Arl2, a small GTP protein whose role is yet largely unknown, appears to be a significant regulator of PP2A content and activity in breast cancer cells, both in vitro and in vivo." (PMID 19829707, 2009).
glioma (5 papers, 2018 to 2021). A benign or malignant brain and spinal cord tumor that arises from glial cells (astrocytes, oligodendrocytes, ependymal cells). "Thirdly, we demonstrated that ARL2 was associated with the regulation of tumorigenicity of glioma cells in vivo." (PMID 29843637, 2018). "ARL2 expression was down-regulated in glioma, and was inversely associated with poor prognosis in glioma patients." (PMID 29843637, 2018). "To examine whether ARL2 expression is associated with glioma patient outcomes, we analyzed the data from CGGA, Rembrandt database, and TCGA to investigate the clinical relevance of ARL2." (PMID 29843637, 2018). "Taken together, these results indicated that ARL2 overexpression inhibited the growth and clonogenicity of glioma cells." (PMID 29843637, 2018). "Secondly, we found that ARL2 overexpression attenuated the proliferation, clone formation, migration, invasive and tumorigenic capabilities of glioma cells by regulating the expression of receptor tyrosine kinase AXL." (PMID 29843637, 2018). "Due to the functional role of ARL2 in glioma, we investigated the downstream target of ARL2 via Gene Set Enrichment Analysis (GSEA)." (PMID 29843637, 2018). "The correlation between ARL2 expression and the outcomes of glioma patients was evaluated with survival data from TCGA, CGGA and Rembrandt dataset." (PMID 29843637, 2018). "Altogether, our data suggest that ARL2 serves as an important suppressor for the proliferation, migration and tumorigenicity of glioma cells by regulating the expression of AXL." (PMID 29843637, 2018). "We then examined ARL2 expression in 20 gliomas tissue samples (grade II, 3 cases; grade III, 9 cases; grade IV, 8 cases) and 3 non-tumor brain tissue samples by immunohistochemistry." (PMID 29843637, 2018). "Firstly, western blot was applied to examine AXL expression in glioma cells infected with ARL2 overexpression or control vector." (PMID 29843637, 2018). "In this study, we investigated the expression of ARL2 in glioma samples by using RT-PCR, immunohistochemistry and western blot." (PMID 29843637, 2018). "The results demonstrated that the upregulation of ARL2 expression resulted in a reduction in subcutaneous growth of U87 glioma cells." (PMID 29843637, 2018). "To further investigate ARL2 expression in glioma, we assessed mRNA and protein levels in a series of clinical glioma specimens and cell lines." (PMID 29843637, 2018). "Based on these observations, we further investigated the effect of ARL2 expression on AXL in glioma cells." (PMID 29843637, 2018). "Secondly, this study provided the evidence that elevated ARL2 expression in glioma cell lines inhibits the abilities of proliferation, clone formation, migration and invasion." (PMID 29843637, 2018). "To investigate the physiological role of ARL2 in glioma, we first overexpressed ARL2 through transducing lentiviral ARL2 vector in glioma cell lines (U87 and U251), and then examined the effects on cell growth." (PMID 29843637, 2018). "The data from CGGA showed decreased ARL2 expression was clinical relevant to the poor prognosis of glioma patients (P = 0.0003)." (PMID 29843637, 2018). "The result showed that ARL2 mRNA levels decreased with the increase in grade of tumor tissues (P < 0.01), as well as U87 and U251 glioma cells (P < 0.0001)." (PMID 29843637, 2018). "Glioma cells with ARL2 overexpression migrated significantly more slowly than control cells (P < 0.05, and H, P < 0.01)." (PMID 29843637, 2018). "We firstly proved that decreased ARL2 expression level was clinically correlated to the higher grades and poorer outcomes of glioma patients." (PMID 29843637, 2018). "In conclusion, this study described the downregulation of ARL2 in clinical glioma samples and its clinical relevance to poor prognosis in glioma patients." (PMID 29843637, 2018).
glioma (continued). "For example, ARL2 overexpression inhibits the malignant phenotypes of glioma cells and predicts better clinical outcomes of glioma patients, while its down‐regulation could suppress the invasion and growth of cervical cancer cells." (PMID 33724652, 2021). "Finally, ARL2 overexpression inhibits proliferation, as well as migration and tumorigenicity of glioma cells, through regulation of the receptor tyrosine kinase AXL, a known regulator of glioma tumorigenesis." (PMID 32426352, 2020). "Additionally, ARL2 downregulation was recently correlated with more aggressive cases of glioma and a lower survival of the patients." (PMID 32426352, 2020). "Although a previous study has shown that ARL2 inhibits glioma proliferation and tumorigenicity by downregulating AXL, the functions of other ARL members in glioma remained unknown." (PMID 31234870, 2019). "To determine whether ARL2 is important to the tumorigenicity of glioma cells in vivo, we injected U87 cells infected with ARL2 overexpression vector or control vector into the flank regions of nude mice and measured tumor volumes every 4 days." (PMID 29843637, 2018). "Taken together, these results demonstrated that ARL2 expression significantly decreased in glioma." (PMID 29843637, 2018). "The aim of this study was to explore the expression and functional role of ARL2 in glioma." (PMID 29843637, 2018). "Similarly, ARL2 protein expression levels were down-regulated in grade IV glioma samples (P < 0.05), as well as U251 and U87 cells than non-tumor samples (P < 0.001)." (PMID 29843637, 2018). "In this study, we investigated the expression and functional role of ARL2 in glioma." (PMID 29843637, 2018). "But the pathophysiologic role and expression pattern of ARL2 in cancer is still controversial, and the function of ARL2 in glioma remains unknown." (PMID 29843637, 2018). "In this study, we identified ARL2 expression pattern and its clinical significance in glioma." (PMID 29843637, 2018). "Furthermore, exogenous ARL2 overexpression attenuated the growth and colony-formation abilities of glioma cells, as well as their migration and invasive capabilities." (PMID 29843637, 2018). "Since microtubule network plays a crucial role in the regulation of cell migration and invasion, wounding healing test and Transwell invasion assay were performed to examine whether ARL2 overexpression inhibited the migration and invasion of glioma cells." (PMID 29843637, 2018). "The downregulation of ARL2 implies the poor prognosis in glioma patients." (PMID 29843637, 2018). "To explore the physiological role of ARL2-AXL axis in glioma cells, we evaluated whether AXL overexpression rescue the phenotype induce by ARL2 overexpression in glioma cells." (PMID 29843637, 2018). "ARL2 inhibited the migration and invasive capabilities of glioma cells." (PMID 29843637, 2018). "Furthermore, our results confirmed that ARL2 reduced the growth, clone formation, migration and invasive abilities of glioma cells, as well as in vivo tumorigenicity." (PMID 29843637, 2018). "Collectively, these results showed that ARL2 could suppress glioma tumorigenicity in vivo." (PMID 29843637, 2018). "Moreover, elevated expression of ARL2 inhibited in vivo tumorigenicity of glioma cells." (PMID 29843637, 2018). "However, the biological functional role of ARL2 in glioma still remains unknown." (PMID 29843637, 2018). "Mechanistically, ARL2 regulated AXL expression, which was known as an important functional regulator of proliferation and tumorigenicity in glioma cells." (PMID 29843637, 2018). "In addition, the restoration of AXL by exogenous expression did not fully rescue the defects in U251 glioma cells caused by ARL2 overexpression, which suggested that there might be additional molecular downstream targets associated with ARL2 overexpression." (PMID 29843637, 2018). "Moreover, the pathophysiologic role of ARL2 in glioma remains unclear." (PMID 29843637, 2018).
glioma (continued). "Altogether, these results indicated that ARL2 overexpression suppressed the expression of AXL and the activation of ERK in glioma cells." (PMID 29843637, 2018). "The expression of ARL family members in TCGA were studied through GlioVis, and ARL2 was significantly differentially expressed between glioma and non-tumor samples." (PMID 29843637, 2018). "Finally, it was proved in this study that ARL2 regulated AXL expression and activated phospho-ERK in glioma." (PMID 29843637, 2018). "Our study suggests that ARL2 inhibits the proliferation, migration and tumorigenicity of glioma cells by regulating the expression of AXL and may conduct as a new prognostic and therapeutic target for glioma." (PMID 29843637, 2018).
hepatocellular carcinoma (5 papers, 2018 to 2023). A malignant tumor that arises from hepatocytes. "Another research indicates that ANRIL improves the mitochondrial function of hepatocellular carcinoma by regulating the miR-199a-5p/ARL2 axis." (PMID 35935642, 2022). "Similar to what was observed in CM, ARL2 upregulation was also described in bladder and cervical cancers, as well as in hepatocellular carcinomas." (PMID 34502169, 2021). "Recent studies have shown that the expression of ARL2 in hepatocellular carcinoma is significantly increased, involved in the cell cycle regulation and DNA replication process of hepatocellular carcinoma, and may be used as a prognostic indicator." (PMID 34163524, 2021). "Recently, ARL2 has been identified as a potential prognosis marker for hepatocellular carcinoma." (PMID 29843637, 2018). "Recent study demonstrates that ARL2 expression is dramatically elevated in hepatocellular carcinoma and might be potentially utilizable as a prognostic marker." (PMID 29843637, 2018). "For instance, LncRNA ANRIL is upregulated in hepatocellular carcinoma (HCC) and promotes the proliferation and mitochondrial function of HCC by regulating Mir-199a-5p/ARL2 axis." (PMID 37370148, 2023).
bladder cancer (4 papers, 2019 to 2023). "On the other hand, miR-195, which is regulated by Urothelial Cancer Associated 1 (UCA1) targets ARL2 in bladder cancer (Li H.-J." (PMID 32426352, 2020). "The authors concluded that the effects in bladder cancer cells mediated by UCA1/miR-195/ARL2 are a consequence of mitochondrial metabolism modulation, which regulates cancer cell survival (Li H.-J." (PMID 32426352, 2020). "For instance, lncRNA UCA1 functions as a ceRNA to enhance mitochondrial function and cell viability in bladder cancer by sponging miR-195 to up-regulate ARL2 expression." (PMID 31531526, 2019). "In addition, studies which aimed to understand the roles of lncRNAs in the metabolism of bladder cancer cells found that UCA1 promotes mitochondrial function in bladder cancer via the miR-195/ADP-ribosylation factor-like 2 (ARL2) signaling pathway." (PMID 36605618, 2023). "Moreover, UCA1 promotes mitochondrial function of bladder cancer via the miR-195/ARL2 signaling pathway." (PMID 30940776, 2019).
breast tumor (4 papers, 2009 to 2021). "In primary human breast tumors, low Arl2 mRNA content is associated with larger tumor size and greater risk of lymph node involvement at diagnosis." (PMID 19829707, 2009). "Tumor size and lymph node involvement in primary human breast tumors according to Arl2 expression levels." (PMID 19829707, 2009). "Here we show, in two different human breast adenocarcinoma models, that Arl2 content has a major impact on breast tumor cell aggressivity both in vitro and in vivo." (PMID 19829707, 2009). "Our results suggest that Arl2 content influences breast tumor growth and aggressivity through a PP2A mediated pathway." (PMID 19829707, 2009). "ARL2 (ADP ribosylation factor‐like 2) is a small GTP protein of the RAS superfamily whose increased expression was correlated with reduced aggressiveness of breast tumour cells." (PMID 33270982, 2021). "Reportedly, ARL2 could affect breast tumor growth and aggressiveness via PP2A-mediated pathway." (PMID 33817293, 2021).
cervical cancer (4 papers, 2018 to 2022). A primary or metastatic malignant neoplasm involving the cervix. "Circ_0084927 sponges miR-142-3p and up-regulates ADP ribosylation factor like GTPase 2 (ARL2) to aggravate the proliferation of cervical cancer cells." (PMID 35365168, 2022). "Similarly, another study reports that ARL2 functions as an oncogene in cervical cancer." (PMID 29843637, 2018).